FASN (fatty acid synthase)
Diseases named in the same sentence as FASN in open-access papers (continued):
Sharing a sentence is not in itself a finding about the gene and the disease.
gastric cancer (42 papers, 2012 to 2026). A primary or metastatic malignant neoplasm involving the stomach. "Previous studies in gastric cancer found that RHOA Y42 mutation in cancer cells produced excessive fatty acids by upregulating fatty acid synthase (FASN)." (PMID 35983074, 2022). "Overexpression of FASN is associated with disease progression and poor prognoses in a variety of malignant tumors, including prostate, breast and gastric cancer." (PMID 32699531, 2020). "FASN is highly expressed in various types of cancer, and is closely associated with tumor stage and prognosis in breast, prostate and gastric cancer." (PMID 32699531, 2020). "Indeed, FASN per se was identified as a poor prognosticator and associated with an inferior immune infiltration in gastric cancer." (PMID 36428733, 2022). "As well, in HER2 + gastric cancer models, the combination of TZ with the FASN inhibitor TVB3166 reverted the anti-HER2 therapy resistance." (PMID 40133809, 2025). "The upregulation of enzymes such as adenosine triphosphate citrate lyase and fatty acid synthase in the tricarboxylic acid cycle has been observed in patients with lung, colorectal, breast, and gastric cancers." (PMID 39883280, 2025). "For example, FASN was overexpressed in gastric cancer tissues, and its expression was negatively correlated with the immune cell infiltration levels of CD4+ T cells, CD8+ T cells, macrophages, neutrophils, and DCs." (PMID 38272906, 2024). "On the other hand, USP38 can deubiquitinate and stabilize FASN in gastric cancer, increasing triglyceride production and promoting growth and migration in gastric cancer cells." (PMID 39048965, 2024). "USP38 enhances gastric cancer progression through deubiquitination and increases the stability of fatty acid synthase." (PMID 39605891, 2024). "Another study demonstrated that interaction between USP38 and FASN enhances the stability of FASN protein and increases triglyceride production in gastric cancer cells, which contributes to cell proliferation, migration, and tumorigenesis." (PMID 38060103, 2023). "Many studies have indicated that FASN can be used as a biomarker for the diagnosis and prognosis of various cancers, such as triple-negative breast cancer, gastric cancer, and glandular cancer." (PMID 37111057, 2023). "By targeting the MTOR/GLI1 signaling pathway, FASN inhibition also lowered gastric cancer development and metastasis." (PMID 35625633, 2022). "In gastric cancer cells, MaCC1, the upstream regulator of FASN, decreased the chemosensitivity to oxaliplatin by enhancing the expression of FASN." (PMID 35646898, 2022). "Among these, we also found the drug cerulenin targeting FASN in stomach cancer was correlated with STAT3 positively (r = 0.555)." (PMID 32486001, 2020). "For instance, ATP citrate lyase and fatty acid synthase are often found overexpressed in gastric cancer tissues, where increased expression of these genes facilitates fatty acid synthesis, providing essential energy and structural support for tumor cell growth." (PMID 40978035, 2025). "Our hypothesis is supported by reports from studies which have shown that FASN knockdown via siRNA can reduce Gli1 levels in gastric cancer cells, suggesting that FASN may contribute to tumorigenesis and metastasis." (PMID 40149597, 2025). "Notably, increased serum FASN levels were detected even in early-stage gastric cancer patients, suggesting its utility as a non-invasive biomarker for early detection." (PMID 41154605, 2025). "Moreover, the HER2-FASN correlation was observed in HER2 + gastric cancer, in which FASN upregulation was correlated with cancer cell stemness and poor prognosis." (PMID 40133809, 2025). "Similarly, another study also reported that FASN expression in gastric cancer tissues was closely related to the levels of immune infiltration of T cells." (PMID 38272906, 2024).
gastric cancer (continued). "Therefore, targeting FASN with USP38 inhibitors can be used as a potential treatment for gastric cancer patients with high expression of USP38." (PMID 39048965, 2024). "High FASN expression has been found in several cancers such as breast and gastric cancer." (PMID 36769200, 2023). "FASN was found to be overexpressed in gastric cancer tissues." (PMID 28180141, 2017). "In a cohort of 87 gastric cancer patients and a control group of 14 individuals, we analyzed the absolute RNA concentration from extracellular vesicles (EV) and the relative levels of FASN, PTEN, and CD44 mRNA, and their correlation with clinico-pathological features." (PMID 34885085, 2021). "In gastric cancer tissues and cells, SREBP-1c is activated and promotes the expressions of FASN and SCD-1 to mediate malignant phenotypes, which has been identified as a potential target for the treatment of gastric cancer." (PMID 35912181, 2022). "In gastric cancer, the enzymes catalyzing the de novo synthesis of FAs (e.g., ACLY, ACC, FASN, and SCDs) were significantly up-regulated." (PMID 35785165, 2022). "In fatty acid anabolism, SREBP1, ACLY, ACSs, ACC, FASN, and SCD1 enhance the occurrence, progression, and metastasis of gastric cancer, and are expected to be potential prognostic markers." (PMID 35625633, 2022). "Fatty acid synthase (FAS) and human epidermal growth factor receptor 2 (HER2) are overexpressed in gastric cancer (GC), and certain interactions have been found between FAS and HER2." (PMID 26622804, 2015). "In gastric cancer, researchers found that USP38, similar to USP2 and USP14, also prevents FASN degradation by removing polyubiquitin chains from the amino acid sequence of FASN, with this process catalyzed by thiol groups." (PMID 40936898, 2025). "In gastric cancer, the activation of SREBP-1c could lead to changes in lipogenic enzymes (e.g., up-regulation of SCD1 and FASN)." (PMID 35785165, 2022). "Furthermore, the srebp-1c-dependent adipogenic pathway can be stimulated by human gastric cancer, promoting the expression of a series of fatty acid synthesis-related genes, such as SCD1 and FASN." (PMID 35785165, 2022). "Additionally, a high FASN level was found to have a significant effect on the poor OS (P = 1.6e-16), FP (P = 1.8e-13), and PPS (P < 1e-16) outcomes for gastric cancer." (PMID 34879004, 2021). "The high expression of FASN has an adverse effect on OS, FP, and PPS in gastric cancer." (PMID 34879004, 2021). "Also included is a set of representative images of immunohistochemical staining of gastric cancer tissues showing four levels of expression of fatty acid binding protein (FABP1) and fatty acid synthase (FASN)." (PMID 28180141, 2017). "The overexpression of fatty acid synthase (FASN) is not only related to the AR of osteosarcoma cells, but also evidenced on gastric cancer (GC)." (PMID 34456997, 2021). "Additionally, since FASN has been shown to be an oncogenic protein, the regulation of FASN by USP38 may not be limited to gastric cancer." (PMID 40936898, 2025). "Fatty acid synthase (FAS) is highly expressed in numerous human cancers and thus could potentially serve as such a biomarker, but the potential utility of measuring FAS for detecting gastric cancer has not been previously investigated." (PMID 24527066, 2014).
liver cancer (42 papers, 2014 to 2025). An epithelial or non-epithelial malignant neoplasm that arises from the liver. "Multiple studies reported that FASN was upregulated in liver cancer, and associated with the malignant progression and poor prognosis." (PMID 39075049, 2024). "It was found that a high FASN mRNA level was associated with poor prognosis in liver cancer patients." (PMID 39075049, 2024). "We have revealed the molecular mechanism by which loss of SIAH1 in liver cancer regulates the protein stability of FASN through two pathways: promoting deubiquitination and reducing ubiquitination." (PMID 39075049, 2024). "The results indicated that FASN was closely associated with liver cancer migration and invasion, and interacted with FSCN1, SIPA1, SPTBN1 and CD59." (PMID 32699531, 2020). "Abnormal expression of FASN in the liver leads to cancer formation, and is associated with tumor progression and poor prognosis in liver cancer." (PMID 32699531, 2020). "In our previous study, FASN was demonstrated to be upregulated in hepatocarcinoma and closely associated with the metastatic potential of liver cancer." (PMID 32699531, 2020). "FASN has also been found to be highly expressed in a wide variety of human cancers, including liver cancer, whereas overexpression of FASN is associated with increasing tumor progression, poor prognosis and risk of death." (PMID 30824767, 2019). "Indeed, previous reports have demonstrated that both hepatitis B and C viruses are able to induce FASN expression, and over-expression of FASN is a typical feature of liver cancer under another predisposing condition, the alcoholic steatohepatitis." (PMID 30591064, 2018). "KAT8 and HDAC4 act as the acetyltransferase and deacetylase of FASN, respectively, regulating FASN protein levels and thereby altering fatty acid synthesis and cell growth in liver cancer cells." (PMID 39778006, 2025). "For instance, cancers such as breast, prostate, and liver cancer commonly exhibit significant upregulation of fatty acid synthase (FASN)." (PMID 40370434, 2025). "In a FASN gene‐knockout hepatic neoplasm mouse model, HMGCR cholesterol synthesis and SREBP‐2 nuclear translocation are elevated." (PMID 40476478, 2025). "It has been shown that FASN can promote the metastasis of liver cancer cells, and its overexpression is closely related to clinical invasiveness and poor prognosis, which was also observed in this study both in human and mice." (PMID 39075049, 2024). "It was found that the protein level of FASN in liver cancer samples was upregulated correspondingly." (PMID 39075049, 2024). "It has been shown that FASN can promote the proliferation, metastasis, and apoptosis of liver cancer cells, therefore playing a key role in liver cancer progression." (PMID 39075049, 2024). "Since UCHL5 exerts its role as a deubiquitinating enzyme through recruitment and activation by ADRM1 (adhesion regulating molecule 1), also known as Rpn13, we further explored the regulation and mechanism of action of ADRM1 on FASN in liver cancer." (PMID 39075049, 2024). "In this study, we determined that ADRM1-activated UCHL5 was upregulated in liver cancer and stabilized FASN through deubiquitinating it, thereby promoting the expression of FSCN1 and filopodia formation in human liver cancer cells, as well as cell movement." (PMID 39075049, 2024). "In this study, we demonstrated that fatty acid synthase (FASN) promoted filopodia formation in liver cancer cells by regulating fascin actin-bundling protein 1 (FSCN1), a marker protein for filopodia." (PMID 39075049, 2024). "Based on these findings, it is reasonable to further explore the regulatory mechanism of high expression of FASN in liver cancer." (PMID 39075049, 2024). "Correspondingly, the protein levels of UCHL5 and FASN also presented a direct correlation in normal and liver cancer specimens." (PMID 39075049, 2024). "Molecularly, the Co-IP assays showed that endogenous UCHL5 interacted with FASN in liver cancer cells." (PMID 39075049, 2024).
liver cancer (continued). "And the mRNA levels of UCHL5 and FASN presented a direct correlation in normal and liver cancer specimens." (PMID 39075049, 2024). "It was found that FASN also plays a positive role in the invasion and migration of liver cancer cells." (PMID 39075049, 2024). "To detect the potential role of FASN in liver cancer, we analyzed the expression level of FASN in human liver cancer tissues and non-tumor tissues using the databases." (PMID 39075049, 2024). "The results revealed that silencing of FASN inhibited filopodia formation in liver cancer cells, while overexpression of FASN produced the opposite effects." (PMID 39075049, 2024). "Since filopodia formation is necessary for cell movement, we analyzed the effects of FASN on invasion and migration of liver cancer cells." (PMID 39075049, 2024). "More precisely, Hep1-6 cells knocked out FASN were implanted beneath the liver capsule to establish an orthotopic model of liver cancer in C57BL/6J mice." (PMID 39075049, 2024). "To determine the role of FASN in filopodia formation, we performed a filopodia localization assay in HepG2 and Huh7 liver cancer cells with different metastases." (PMID 39075049, 2024). "Our results reveal a novel mechanism for FASN accumulation due to the low expression of SIAH1 in human liver cancer and suggest an important role of FASN in filopodia formation in liver cancer cells." (PMID 39075049, 2024). "In this study, we highlight the effect and mechanism of FASN on filopodia formation in liver cancer cells." (PMID 39075049, 2024). "Using human HCC cell lines and mouse models of hepatocarcinogenesis, we revealed that SKP2 is a FASN downstream effector in liver cancer driven by AKT." (PMID 39064589, 2024). "Further analysis of clinical data revealed a correlation between the expression of FASN and the clinicopathological characteristics of liver cancer patients." (PMID 39075049, 2024). "It was found that UCHL5 facilitated filopodia formation in liver cancer cells by regulating FSCN1, which was associated with FASN." (PMID 39075049, 2024). "In liver cancer cells, acetate-induced lipogenesis is regulated by ACSS2 and ACSS1 and is associated with regulation of FASN expression." (PMID 38818373, 2024). "In conclusion, the current study identified that FASN is upregulated in liver cancer and then promotes filopodia formation and metastasis of liver cancer cells by regulating FSCN1 and other pathways." (PMID 39075049, 2024). "SPIN1 triggers FASN signals through SREBP1c to regulate abnormal liver lipid metabolism and promote liver cancer cell growth." (PMID 35070947, 2021). "In the current study, FSCN1 and SIPA1 were significantly downregulated following FASN knockdown in liver cancer cells." (PMID 32699531, 2020). "In the case of liver cancer (HepG2) cells, Qu induced apoptosis via inhibition of FASN (fatty acid synthase), a metabolic enzyme that is usually upregulated during early stages of tumorigenesis." (PMID 33192517, 2020). "The identification of the protein complexes will provide an increased understanding of the FASN interactome, and has the potential to elucidate the molecular mechanisms involved in liver cancer invasion and metastasis." (PMID 32699531, 2020). "Wound healing and Transwell assays was performed to observe the effect of FASN during migration and invasion in liver cancer." (PMID 32699531, 2020). "Elevated expression of SCD and FASN in cancer cells is related to markedly worse prognosis in many human cancers, including liver cancer." (PMID 31083642, 2019). "FASN, a key enzyme involved in de novo lipogenesis, supports the high metabolic demands of cancer cells and has been shown to correlate with tumor aggressiveness and reduced survival in liver cancer patients." (PMID 41002582, 2025). "To confirm whether SIAH1 affects filopodia formation in liver cancer cells by regulating FASN, we detected the regulation of FSCN1 by SIAH1." (PMID 39075049, 2024).
liver cancer (continued). "Both the two pathways participate in the regulation of FASN in liver cancer." (PMID 39075049, 2024). "Our study has demonstrated the oncogenic effect and regulatory mechanism of FASN in liver cancer, which will provide new insights for further study of the molecular mechanism of liver cancer metastasis and molecular targeted therapy for liver cancer." (PMID 39075049, 2024). "To seek alternative combined therapies that could improve the survival of liver cancer patients through targeting CSCs, we combined a conventional targeted therapy drug, sorafenib, with the FASN inhibitor, cerulenin, for potential treatment." (PMID 39332525, 2024). "The evidence suggests that FASN can impact the metastasis of liver cancer through various pathways." (PMID 39075049, 2024). "Both the two pathways are involved in the regulation of FASN in liver cancer." (PMID 39075049, 2024). "The mRNA level of FASN in liver cancer tissues was upregulated." (PMID 39075049, 2024). "Interestingly, when investigating the correlation between FASN regulation of filopodia formation and invasion and migration of liver cancer cells, we observed that inhibiting filopodia formation did not completely impede cell motility." (PMID 39075049, 2024). "The results showed that SIAH1 could decrease the expression of FSCN1 by directly ubiquitinating FASN, thereby inhibiting filopodia formation in human liver cancer cells, as well as cell invasion and migration." (PMID 39075049, 2024). "Indeed, silibinin reduces FASN protein expression, thereby decreasing the impact of obesity in liver cancer." (PMID 36670988, 2023). "Inhibition of FASN expression could suppress malignant tumor cell proliferation in vitro and in vivo in oral squamous cell carcinomas, liver cancer, and neurogenesis." (PMID 35350838, 2022). "The SPIN1 stimulates the growth of liver cancer via the SREBP1c-triggered FASN signaling pathway." (PMID 34552769, 2021). "Knockdown of FASN in liver cancer reduced the expression of FSCN1, SIPA1, SPTBN1 and CD59." (PMID 32699531, 2020). "Here, we evaluated the specific contribution of FASN in this process, namely we assessed whether FASN suppression affects the growth of c-MYC liver cancer cells in vitro." (PMID 33187130, 2020). "The levels of these proteins were decreased by FASN knockdown, indicating that FASN may modulate the expression of these proteins to influence the progression of liver cancer." (PMID 32699531, 2020). "A similar approach may be possible by targeting FATP1, as suppression of FATP1 was shown to enhance the pro-apoptotic and anti-proliferative effect of FASN silencing in liver cancer cells." (PMID 33083663, 2020). "Additionally, wound healing and Transwell assay demonstrated that downregulation of FASN weakened liver cancer migration and invasion capacity." (PMID 32699531, 2020). "Furthermore, the inhibition of FASN has been shown to have an anti-cancer effect in a wide variety of cancers and FASN was found to be highly expressed in liver cancer cells." (PMID 30824767, 2019). "Moreover, it has also been demonstrated that fatty acid synthase is up-expressed in liver cancer and promotes the synthesis of endogenous fatty acids that supply energy used for the cancer progression." (PMID 30373285, 2018). "The present study showed that quercetin induced liver cancer cell apoptosis via inhibition of FASN." (PMID 25009654, 2014). "In the present study, it was found that quercetin could induce apoptosis in human liver cancer HepG2 cells with overexpression of FASN." (PMID 25009654, 2014). "Thus, we investigated the mechanisms of FASN protein degradation or stabilization in liver cancer." (PMID 39075049, 2024). "To investigate the clinical significance of UCHL5 and FASN, we first detected the mRNA level of UCHL5 in liver cancer via database." (PMID 39075049, 2024). "Using liver cancer cell lines, mouse models, and human specimens, we found that SKP2 is a critical effector of FASN in this aggressive tumor." (PMID 39064589, 2024).